RNU6-120P (RNA, U6 small nuclear 120, pseudogene)
Gene: Small nuclear RNA gene on chromosome 18 (21,120,404 to 21,120,506, reverse strand). Ensembl gene ENSG00000251886.
Homologues: Orthologues: chimpanzee U6 (99% identical), macaque U6 (69% identical), guinea pig U6 (68% identical). Paralogues in human: RNU6-1024P (78% identical), RNU6-1060P (78% identical), RNU6-1131P (78% identical), RNU6-1147P (78% identical), RNU6-487P (78% identical), RNU6-1287P (77% identical), RNU6-15P (77% identical), RNU6-193P (77% identical), RNU6-558P (77% identical), RNU6-665P (77% identical), RNU6-820P (77% identical), RNU6-843P (77% identical), and 1282 more.